BECN1 (beclin 1)
Diseases named in the same sentence as BECN1 in open-access papers (continued):
Sharing a sentence is not in itself a finding about the gene and the disease.
tumor (continued). "Finally, the pro-autophagic BECN1 gene expression was significantly (p ≤ 0.05) downregulated in DXN-CSNP, PL-CSNP, PL + DXN, Kmp, and Kmp + DXN groups as compared to the untreated EST-tumor group." (PMID 38253759, 2024). "Additionally, in a xenograft model, immunohistochemical analysis of tumor tissues showed that the LC3 and Beclin-1 proteins were highly expressed in the tumors from the ginsenoside Rg1-treated nude mice, confirming that ginsenoside Rg1 also induced autophagy in vivo." (PMID 38668684, 2024). "In addition, PD‐L2 can also induce autophagy through beclin‐1, as another upstream signal of the RhoA‐ROCK‐LIMK2 signaling pathway, beclin‐1 can also control cellular autophagy by regulating RhoA‐ROCK‐LIMK2 signaling pathway and also influence the tumor metastasis." (PMID 38800967, 2024). "Moreover, knockout of neither Beclin-1 nor hVPS34 gene eliminated resveratrol-induced autophagosome formation, suggesting the existence of a non-classical pathway independent of tumor suppressor Beclin-1." (PMID 36755953, 2023). "Importantly, ectopic expression of Beclin 1, but not Beclin 1S90+93A, remarkably rescued the tumor growth inhibited by USP5 depletion." (PMID 36528652, 2022). "However, the deletion of BECN1 in human cancers and the deletion of the breast cancer 1 (BRCA1) gene cannot be disassociated, which indicates that BECN1 is not a tumor suppressor in most human cancers." (PMID 36197606, 2022). "However, follow-up studies suggested that BECN1 could be a passenger gene of the neighboring tumor suppressor gene, BRCA1, raising concerns about the roles of BECN1 and autophagy as tumor suppressors." (PMID 35727403, 2022). "In addition, BECN1 and ULK1 have been shown to promote tumor growth in various cancers." (PMID 36177001, 2022). "Interestingly, the four patients with a low BECN1 and high LC3 tumor (two of them underwent chemotherapy and two did not) showed a much better prognosis (not significant; p = 0.37) than the five patients with a high BECN1 and low LC3 tumor." (PMID 33925189, 2021). "Negative expression of Beclin-1 gene may determine aggressive tumor behavior reflected by the overall survival." (PMID 33906303, 2021). "Furthermore, the expression of Bcl-2 and Beclin-1 in tumor tissues was not correlated (Spearman’s correlation: p > 0.05, r = 0.047)." (PMID 34257544, 2021). "Given the role of autophagy in suppressing chromosomal instability, it was not unreasonable that BECN1 might act as a tumor suppressor." (PMID 31923184, 2020). "Natural polyphenolic compounds, including flavonoids and non-flavonoids, execute their anticarcinogenic mechanism through upregulating tumor suppressors and autophagy by modulating canonical (Beclin-1-dependent) and non-canonical (Beclin-1-independent) signaling pathways." (PMID 32121322, 2020). "Accumulation of SQSTM1/p62, as well as LC3 and BECN1 in poorly differentiated OSCC, is correlated with immune infiltration of T cells and TAMs, revealing that autophagic inhibition during advanced stages of the OSCC is relevant to establish a tumor immune niche." (PMID 33363032, 2020). "Therefore, by targeting autophagy through Becn1 and CCL5, NK cell filtration to the tumor could increase and prevent tumor immune escape." (PMID 31396523, 2019). "Similarly, the expression of Beclin-1, LC3 and p62, which are well studied autophagy genes were also upregulated, indicating that EAC tumor induces lysosomal biogenesis and autophagy, which could be causing atrophy in mice hearts." (PMID 29618792, 2018). "Moreover, the ECD, which is crucial for recruiting VPS34 is necessary for inducing autophagy as well as tumor suppression, suggesting that the tumor suppressor function of BECN1 is coupled to the lipid kinase function, rather than BCL2 association." (PMID 30370269, 2018).
tumor (continued). "Moreover, in vivo xenograft models, the mice given stable overexpressed miR-590-3p cells and treated with EMAP-II and TMZ had the smallest tumor sizes, besides, miR-590-3p + EMAP-II + TMZ up-regulated the expression level of miR-590-3p, LC3-II and Beclin-1 as well as down-regulated p62/SQSTM1." (PMID 28348518, 2017). "Tumor tissues were then fixed and paraffin-embedded sections were prepared for immunohistochemical examination to compare the expression of Lewis y antigen, p27, the level of ubiquitination, and autophagy-related proteins (LC3, p62 and Beclin 1) in the two groups." (PMID 29299130, 2017). "Besides, Beclin 1 is not the only one gene which binds autophagy and tumor, several oncogenes or tumor suppressor genes affect autophagy-related pathways, the PTEN tumor suppressor genes and the Akt, Ras or Myc oncogenes, for example." (PMID 28915706, 2017). "However, the autophagic and tumor suppressive roles of Beclin 1 remain a major research focus, and the exact mechanism by which Beclin 1 acts as a tumor suppressor has not yet been fully understood." (PMID 28345663, 2017). "Regarding tumor cell survival, the resistance to metabolic stress induced by TMEM74 overexpression was counteracted by ATG5, ATG7, ATG16L1, ATG3 and ATG10 deficiencies but not the BECN1 and ULK1." (PMID 29048433, 2017). "Therefore, ASPP2 is a key regulator of BECN1-dependent autophagy, and decreased ASPP2 may contribute to tumor progression and chemoresistance via promoting autophagy." (PMID 27929538, 2016). "Although we found that manipulations of Beclin 1 or Beclin 2 level did lead to change in autophagy, their effects on tumor growth may not entirely directly due to autophagy." (PMID 26506105, 2015). "It is conceivable that initial disruption of Beclin-1 and autophagy forces adaptation of the autophagic machinery to no longer depend upon Beclin-1, yet a role for this protein in maintaining tumor cell viability may select for its continued expression." (PMID 26239434, 2015). "In case 1, the expression of BCL-2 was quite high, which could account for inhibition of BECLIN 1 proautophagic activity, and in fact this tumour was negative for LC3 staining." (PMID 25136588, 2014). "The low Beclin 1 mRNA levels detected in our HCC tissues (compared with CH and CIRR without tumor) support the hypothesis that a downregulated autophagy can contribute to tumor progression." (PMID 22928777, 2012). "Beclin-1, a core molecule responsible for regulating autophagosomes in post-infection autophagy, has a BH3 binding domain and can bind to a variety of anti-apoptotic Bcl-2 family proteins, which may have direct pro-apoptotic and anti-autophagic effects on tumor cells." (PMID 38932177, 2024). "However, they could not exclude the possibility that Beclin-1 heterozygosity might also delay tumor development by compromising the survival of developing malignant cells." (PMID 35453338, 2022). "However, an interesting phenomenon was that the expression of BECN1 in poorly differentiated NSCLC tissues was higher than in well- and middle-differentiated tissues, indicating that the roles of BECN1 might be different according to tumor malignancy." (PMID 31272261, 2019). "Recent studies revealed that CISD2-BCL2 complex may negatively modulate the BECN1 autophagy-initiating complex via PIK3C3 and regulate endoplasmic reticulum (ER) Ca2+ homeostasis via ER inositol 1,4,5-triphosphate receptor (ITPR/IP3R) and contributes to tumor carcinogenesis and progression in LSCC." (PMID 27007153, 2016).
tumor (continued). "In FL, significantly decreased expression of p62, LC3 and Beclin-1 was observed in both intra-follicular and non-malignant inter-follicular areas, suggesting autophagy may be altered in both malignant FL cells and surrounding tumor infiltrating cells." (PMID 25362242, 2014). "Mice that are hemizygous for BECN1 and those that lack Atg4C and BIF1 exhibit a heightened likelihood of tumor formation due to the absence of these autophagic factors." (PMID 40248706, 2025). "We conclude that tumor cell proliferation under metabolic drug treatment is not only dependent on ATG7, but also to an equal extent on BECN1, LC3, and ATG10." (PMID 35681458, 2022). "On the other hand in mice, knockdown of Atg7 but not Becn1 decreased numbers of tumors formed by dormancy-prone cells in a TGFβ-induced inflammatory background, indicating that requirement for Becn1 gene in dormancy-related autophagy and tumor cell survival might be tumor and cell type-dependent." (PMID 33816262, 2021). "Last but not least, CD147 can down-regulate Beclin 1 and inhibit starvation-induced autophagy through the PI3K/Akt/mTOR pathway, modulating the apoptosis of tumor." (PMID 28881651, 2017). "Next we studied the expression of Beclin 1, LC3B and Bcl-xL in both the center of tumor (CT) area and noncancerous mucosal (NM) region." (PMID 25762626, 2015). "The expressions of Beclin 1, LC3B and Bcl-xL in both tumor area and adjacent noncancerous mucosal region were also associated with overall survivals." (PMID 25762626, 2015). "In our study, Beclin 1 and LC3B were more likely under-expressed in the central tumor area compare to those in the adjacent noncancerous mucosal regions; while Bcl-xL showed the reversed expression patterns." (PMID 25762626, 2015). "Next immunohistochemical study showed the expressions of Beclin 1, LC3B and Bcl-xL in both the center of tumor and adjacent noncancerous mucosal region were also correlated with overall survivals." (PMID 25762626, 2015). "Here we detected the expressions of Beclin 1, LC3B and Bcl-xL in both tumor and adjacent noncancerous regions from 526 CRC patients." (PMID 25762626, 2015). "The negative expression of Beclin-1 and LC3B in cervical SCC with hrHPV infection was found to promote a higher clinical tumor node metastasis (TNM) stage and lymph node metastasis." (PMID 25202355, 2014). "Statistics was then applied to the whole group of tumours analyzed for LC3 positivity, including both the BECLIN 1 positive and BECLIN 1 negative." (PMID 25136588, 2014). "Western blot analysis of tumor tissues showed no significant changes in c-MYC protein levels but revealed reduced PTBP1 protein and c-MYC S62 phosphorylation levels, along with increased levels of Atg10, Beclin-1, P62, and LC3B." (PMID 40469179, 2025). "It was found first in mice hemizygous for BECN1 and later in mice lacking Atg4C and BIF1 that lack of these autophagic factors could lead to increased tumor formation incidence." (PMID 40248706, 2025). "Regardless of whether BECN1 is a tumor suppressor gene or not, another autophagy-related gene, PARK2 (Parkin), has been identified as a potential tumor suppressor that is frequently deleted in human tumors." (PMID 30678689, 2019).
tumor (continued). "Considering that IR-induced tumour cell death in vitro fails to explain some clinical observations in vivo, we decided to evaluate the effect of ATG5 and Beclin 1 depletion on the growth of irradiated A549 tumour xenografts implanted in immunodeficient BALB/c nude mice (which lack T lymphocytes)." (PMID 24037090, 2014). "Furthermore, HULC overexpression in vivo induced tumor formation, and reduced ATG7, LC3 expression, while inducing SQSTM1 expression; however, we found that HULC overexpression did not influence ATG5, ATG12, Beclin-1, VPS34, P150 or UVRAG expression." (PMID 29022892, 2017). "When restricted to the group of BECLIN 1-positive tumours, it was found that 20 out of 21 patients bearing a tumour also positive for LC3 were still alive, while 6 out of 9 of those patients bearing a tumour negative for LC3 were DOD, at 5 years after diagnosis." (PMID 25136588, 2014).
cancer (658 papers, 2008 to 2025). A tumor composed of atypical neoplastic, often pleomorphic cells that invade other tissues. "Significance: Deadly cancers with BAP1 mutations suppress autophagy by phosphorylating the autophagy regulator BECN1 via the proto-oncogene SRC." (PMID 40754831, 2025). "For example, the single allelic deletion of the autophagy-related gene Beclin-1 in various human cancers reduces autophagy activity, thereby increasing the risk of cancer." (PMID 40842844, 2025). "In cancer, Beclin-1 is often dysregulated, exhibiting loss-of-function mutations or diminished expression in several malignancies, including breast, ovarian, and prostate cancers." (PMID 40710325, 2025). "We then explored the methylation levels (beta-values, HumanMethylation450) of MAP1LC3A, OPTN, PINK1, PRKN, SRC, BNIP3L, and BECN1 in pan-cancer and their association with gene expression and the immune cell infiltrates." (PMID 39859167, 2025). "Numerous studies have demonstrated that targeting autophagy-related proteins, such as ATG5 or Beclin-1, can increase the susceptibility of cancer cells to necroptotic death, highlighting the therapeutic potential of this interaction." (PMID 40710325, 2025). "Next, we assessed the impact of LCN2 uptake from cancer cells co-cultured with BECN1-deficient adipocytes." (PMID 38744820, 2024). "Beclin1 (BECN1), a haploinsufficient tumor suppressor, plays a crucial role in regulating autophagy and has been implicated in the tumorigenesis of various cancer types." (PMID 39329702, 2024). "In line with BECN1-deficient adipocytes, cancer cell-co-cultured adipocytes exhibited elevated YAP/TAZ nuclear translocation and β-catenin levels." (PMID 38744820, 2024). "A reduced Beclin 1 expression is associated with impaired autophagy in cancer, making it a significant biomarker associated with carcinogenesis and progression." (PMID 39664581, 2024). "An illustrative example is the tumor suppressor gene Beclin 1, which is implicated in the initiation of autophagy in the context of cancer." (PMID 39664581, 2024). "When grown with BECN1-deficient adipocytes, cancer cells exhibited an enhanced proliferation rate in a dose-dependent manner." (PMID 38744820, 2024). "The potential of Beclin-1 as a viable target for cancer therapy is highlighted by its associations with key autophagy regulators such as AMPK, mTOR, and ATGs." (PMID 39650649, 2024). "Specifically, we investigated the impact of BECN1 loss in fibroblasts on cancer malignancy, presenting a potential avenue for further research." (PMID 38744820, 2024). "Among the genes associated with autophagy, the BECN1 gene represents the first link between autophagy and cancer." (PMID 36830954, 2023). "Although BECN1 mutations have been identified in gastric and colorectal cancers, their occurrence in the general cancer landscape is extremely rare." (PMID 37887330, 2023). "Beclin-1 deletion increases the chance of developing cancer in humans, while its deficiency has been linked to the onset of solid tumors." (PMID 36769263, 2023). "Here, we report on the isolation and molecular and functional characterization of three BECN1 transcript variants (named BECN1-α, -β and -γ) in human cancer cells." (PMID 36008963, 2022). "The BECN1 gene is essential for early embryonic development and its perturbation is linked to the onset of several human diseases including cancer, and cardiovascular and neurodegenerative diseases, as well as the response to pathogen infection." (PMID 35585060, 2022). "Compared with adjacent normal tissue, Beclin 1 expression was elevated in the cancer tissue significantly; assessments of EGFR and ALK mutations showed that out of the 480 patients, 233 (48.5%) and 75 (12.6%) patients had EGFR and ALK mutations." (PMID 36401689, 2022). "DAPK1 expression induced autophagy and apoptotic activity in various cancers by causing autophagic cell death via reducing the interaction between Beclin-1, Bcl-2, and Bcl-XL." (PMID 35321516, 2022).